MTOR (mechanistic target of rapamycin kinase)
Diseases named in the same sentence as MTOR in open-access papers (continued):
Sharing a sentence is not in itself a finding about the gene and the disease.
gastric cancer (continued). "In addition, GOLPH3 may primarily activate the Akt/mTOR signaling pathway via the activated mTORC1 complex rather than the mTORC2 complex, resulting in p70S6 and 4E-BP1 phosphorylation, thereby affecting gastric cancer." (PMID 25286393, 2014). "However, with the exception of the ErbB2-targeting antibody, targeting agents, including PI3K/Akt/mTOR inhibitors, have not been approved for treatment of patients with gastric carcinoma." (PMID 25003395, 2014). "Therefore, we hypothesized that in KRAS mutant gastric cancer cells, the blockade of both PI3K/AKT/mTOR and KRAS/mTOR/STAT pathways using NVP-BKM120 and AG490 would be synergistic." (PMID 22159814, 2012). "The rate of negative p-mTOR in gastric cancer was similar to that in another study." (PMID 19223902, 2009). "mTOR and phospho-p70S6K proteins were examined by immunohistochemistry on tissue microarray containing gastric carcinomas (n = 412), adenomas (n = 47) and non-neoplastic mucosa (NNM, n = 197) with a comparison of their expression with clinicopathological parameters of carcinomas." (PMID 20003385, 2009). "However, the mTOR/p70S6K signaling pathway in gastric carcinomas has not been investigated so far, which impel the authors to investigate the role of mTOR/p70S6K signaling pathway for finding a novel target for the anticancer drugs in gastric carcinoma." (PMID 20003385, 2009). "Taken together, these data show that the early growth phase of GLI2A-expressing gastric cancers, but not tumor initiation, is dependent on mTOR/S6 signaling, which may promote tumor growth partly by maintaining cells in an undifferentiated, proliferative state." (PMID 26859571, 2016). "The lack of an association of mTOR signalling and MMP expression might be due to the interplay with pathways that are involved in regulation of mucosal inflammation which are dependent on the very complex tissue microenvironment within gastric cancer." (PMID 26652716, 2015). "Here we showed that pAMPKα and PTEN were down-regulated and p-mTOR, p-S6, p-4EBP1, MMP7, and DCN1 were up-regulated in human gastric cancer tissue samples as compared to that in the noncancerous tissues." (PMID 25909163, 2015). "In the present study with a small cohort of patients, we observed a higher expression of p-mTOR, pS6, p4EBP1, PTEN, and MMP7 proteins in primary gastric cancer tissues than in matched noncancerous tissues." (PMID 25909163, 2015). "This is further supported by our previous result that the SNU-668 cell line is less sensitive to dual PI3K/mTOR inhibitor NVP-BEZ235, compared to other gastric cancer cell lines (data not shown)." (PMID 22159814, 2012). "While the data presented here is focused on human circulating B-lymphocytes our conclusions are supported by studies in gastric cancer where MMP-7 and MMP-2 expression did not correlate with mTOR activation and Rapamycin failed to decrease MMP-7 secretion despite decreasing mTOR phosphorylation." (PMID 28634370, 2017).
colorectal cancer (695 papers, 2008 to 2026). A primary or metastatic malignant neoplasm that affects the colon or rectum. "The results presented in here, although preliminary, opens up the possibility to investigate further the role of mTOR in colorectal cancer relapse risk." (PMID 40269326, 2025). "mTOR inhibitors are mainly used in colorectal cancer patients with PIK3CA mutations, in combination with chemotherapy or other drugs, in order to improve efficacy and overcome resistance." (PMID 39555098, 2024). "Among these miRNAs, miR-1185 was shown to be down-regulated in colorectal cancer cells in association with the mTOR pathway." (PMID 39769441, 2024). "Some studies have shown that PIK3CA gene mutations can increase the sensitivity of colorectal cancer to mTOR inhibitors." (PMID 39555098, 2024). "In contrast, Lactobacillus X12 inhibited the growth of colorectal cancer cells by inhibiting mTOR and regulating cell-cycle-associated proteins p27 and E1." (PMID 37511569, 2023). "On the other hand, analysis of downregulated transcripts after knockdown of DIS3L2 showed enrichment in pathways associated with multiple types of cancers, namely “colorectal cancer”, including “regulation of actin cytoskeleton” and “mTOR signaling pathway”." (PMID 37340282, 2023). "In colorectal cancer, p-mTOR overexpression was significantly associated with the occurrence of distal and lymph node metastasis." (PMID 35201501, 2022). "We also analyzed components of the affected pathways, including RAS, WNT, NOTCH, Hippo, MYC, TGF-beta, and other pathways associated with the development of colorectal cancer, and compared them between the low and high MTOR expression groups." (PMID 35883111, 2022). "As an adjuvant and complementary drug, Curcumin showed anticancer activity through inhibition of Wnt/β-catenin, Notch and PI3K/Akt/mTOR signaling pathways associated with colorectal cancer development." (PMID 35922850, 2022). "Mutations in the gene encoding for the alpha catalytic subunit of kinase PI3K, PIK3CA, are the most common colorectal cancer mutations in the PI3K/AKT/mTOR signal transduction pathway and are present in 20% to 25% of colorectal cancers." (PMID 36295658, 2022). "Because progranulin also prevents apoptosis in breast and colorectal cancer cells via mTOR independent manner, it is conceivable that progranulin depletion causes apoptosis via mTOR independent manner in hematopoietic cancer cells as well." (PMID 33490663, 2021). "IL6 ectopic expression enhanced PP242 drug susceptibility in colorectal cancer cells, which completely abolished the activity of mTOR pathway." (PMID 33582655, 2021). "We demonstrated that the CSC-suppressive effect of metformin was associated with AMPK activation/mTOR inhibition and repression of protein prenylation through suppression of mevalonate pathway in colorectal cancer." (PMID 32911743, 2020). "It has also been shown that PI3K/Akt/mTOR inhibitor treatments have minimal activity against advanced colorectal cancer with PIK3CA-mutations including E545K, M1043V and H1047R and that concomitant KRAS mutations frequently contribute to this resistance." (PMID 31769426, 2019). "Conversely, in the colorectal-cancer samples the PIK3CA activating mutation was more frequently associated low mTOR activity." (PMID 29137436, 2017). "For example, mTOR is overexpressed in colorectal cancers, and several carcinomas are found to contain a single amino acid mutation that leads to mTOR constitutive activation." (PMID 25944097, 2015). "Down-regulation of miR-144 is associated with colorectal cancer progression via activation of the mTOR signalling pathway." (PMID 26395400, 2015). "By targeting MCL-1 via mTOR inhibition, colorectal cancers with Kras or BRAF mutations are sensitized to BCL-2/BCL-XL inhibition." (PMID 26134786, 2015).
colorectal cancer (continued). "In the present review we have focused on the role for mTOR in orchestrating key physiological and pathological processes, with a particular emphasis on colorectal cancer (CRC), which remains the second leading cause of cancer death in the United States." (PMID 24393708, 2014). "Conversely, coexisting KRAS mutations confer the resistance of PIK3CA mutant colorectal cancer to PI3K/mTOR inhibitors in preclinical and in clinic studies." (PMID 23826249, 2013). "While previous studies highlighted CA’s ability to induce apoptosis in breast and colorectal cancer via albumin nanoparticles, and trigger apoptosis while inhibiting Akt/mTOR signaling in GC, the precise mechanisms underlying its impact on GC chemosensitivity were unclear." (PMID 40696490, 2025). "This miRNA may be associated with Parkinson’s disease, the mTOR signalling pathway, thyroid cancer, and colorectal cancer, suggesting greater functional value in milk from extensive than intensive dairy farms." (PMID 39457889, 2024). "BHD may predispose patients to colorectal cancer because of folliculin’s role in AMPK/AKT/mTOR signaling and its inhibition of LDHA, synergizing with the more familiar APC pathway through established intermediaries of cell growth." (PMID 36859772, 2023). "Despite the key function of PI3K/AKT/mTOR activity in a sub-set of BRAF mutated colorectal cancers, few trials have attempted to target the pathway in these cancers or to systematically exploit therapeutically the sub-set with concomitant BRAF and PIK3CA mutations." (PMID 36079062, 2022). "In summary, we have shown that rs10138227 AKT1 gene variation in the PI3K/AKT/mTOR pathway may be associated with the risk of colorectal cancer." (PMID 33247671, 2020). "Importantly, while loss of USP22 expression resulted in increased tumor growth and aggressiveness, activation of the mTOR pathway resulted in a synthetic vulnerability of USP22-deficient colorectal cancer cells to mTOR inhibitor treatment." (PMID 31801945, 2019). "Indeed the inhibition of mTOR in BRAFV600E cells counteracts the metabolic predisposition and demonstrates mTOR as a potential target in BRAFV600E-driven colorectal carcinomas." (PMID 29907857, 2018). "c-Myc associates with the resistance to mTOR inhibitors in breast and colorectal cancers." (PMID 29228674, 2017). "Metformin may reduce colorectal cancer risk by activating adenosine monophosphate-activated protein kinase and by consequent inhibition of the mammalian target of rapamycin (mTOR)." (PMID 27766252, 2016). "In summary, we have shown that the decreased expression or activation of key survival molecules following treatment with PI3 Kinase/mTOR inhibitor PI-103 or HSP90 inhibitor 17-AAG in combination with TRAIL was associated with enhanced apoptosis in TRAIL-resistant colorectal cancer cells." (PMID 23852390, 2013). "Considering the important functions of CSCs, it is interesting to explore whether therapeutic agents targeting the PI3K/mTOR signaling pathway are effective in colorectal cancer driven by CSCs harboring a somatic PIK3CA mutation." (PMID 23826249, 2013). "Furthermore, a phase I study of a recently developed mTOR inhibitor found that colorectal cancer patients with PIK3CA mutations had a higher response rate than those without mutations." (PMID 22994622, 2012). "Altogether, in vivo results suggest that NaB treatment is correlated to the mTOR-dependent ferroptosis and consequent tumor growth through xenografts and colitis-associated colorectal tumorigenesis, implicating the potential clinical applications of NaB for future colorectal cancer treatments." (PMID 37185889, 2023). "A recent study stated that diet and gut microbes could jointly act as enhancers of the programmed cell death to reduce colorectal cancer, and in humans, the bacterial community is a rich source of metabolites against pathogenic fungi, via the activation of the mTOR signalling pathway." (PMID 35602034, 2022).
colorectal cancer (continued). "Besides ovarian cancer, this pathway is also reported in colorectal cancer, with the genes associated with colorectal cancer-inhibiting the proliferation of colorectal cancer cells and promoting apoptosis through the inhibition of the mTOR signaling pathway." (PMID 33968741, 2021). "Furthermore, mammalian target of rapamycin (mTOR) may be associated with its upstream Akt in pristimerin-induced inhibition of migration and invasion in colorectal cancer HCT-116 cells." (PMID 31354475, 2019). "Through this pathway, oncogenic AKT and mTOR trigger protein synthesis to stimulate the expansion and reproduction of colorectal cancer cells while inhibiting the apoptosis of cancer cells." (PMID 41584038, 2026). "trilobata induces autophagic cell death through ROS-mediated Akt/mTOR inhibition, supporting its potential as a source of innovative colorectal cancer therapeutics." (PMID 42196610, 2026). "A research indicates that IFI35 promotes CD8+ T cell proliferation and cytotoxic activity through the PI3K/AKT/mTOR pathway in colorectal cancer, thus suppressing tumor growth." (PMID 40463715, 2025). "Functional heterogeneity exists among subtypes: FABP7 drives glioblastoma stem cell migration via RXRα signaling, while FABP5 exhibits context-dependent roles, promoting HCC progression but suppressing colorectal cancer (CRC) through mTOR-mediated autophagy." (PMID 40717587, 2025). "The LARP1/mTOR axis has been shown to facilitate the proliferation and metastatic spread of epithelial and colorectal cancers." (PMID 39786317, 2025). "While our study specifically investigates genetic mutations in the MAPK and JAK/STAT pathways, we acknowledge that alterations in other pathways, such as the PI3K/AKT/mTOR pathway, also play critical roles in colorectal cancer progression." (PMID 40227607, 2025). "ESM1 promotes angiogenesis in colorectal cancer by activating the PI3K/Akt/mTOR pathway, a mechanism that accelerates tumor progression." (PMID 40722723, 2025). "Additional examination indicated that the PI3K/AKT/mTOR pathway plays a vital role in determining the effectiveness and outlook of phillyrin treatment in colorectal cancer." (PMID 41142018, 2025). "Increased ATP production leads to AMPK inhibition and mTOR activation, promoting the proliferation and metastasis of colorectal cancer cells." (PMID 41421797, 2025). "This is due to their ability to inhibit the Wnt/β-catenin and mTOR signaling pathways, which are known to play a role in the development and progression of colorectal cancer." (PMID 40059876, 2025). "It exerts a protective effect against apoptosis in normal cells, particularly in myocardial cells, while inducing apoptosis in colorectal cancer cells via the PI3K/AKT/mTOR pathway." (PMID 40942095, 2025). "Given previous reports of RAB1A-mediated mTOR regulation in colorectal cancer, we downregulated RAB1A expression of two human PCa cell lines with RAB1A-targeting shRNA lentiviruses." (PMID 41050665, 2025). "The effect of NEDD4L inhibits the AKT/mTOR signaling pathway to decrease colorectal cancer cell proliferation, consequently suppressing colonization." (PMID 40279519, 2025). "This decrease in the methylarginine level of AKT1 leads to the inhibition of the AKT/mTOR signaling pathway and a subsequent decrease in colorectal cancer cell proliferation." (PMID 40279519, 2025). "In conclusion, our results demonstrated that UA can inhibit cell growth and cell cycle progression in Wnt-stimulated P19 cells and colorectal cancer cells by targeting β-catenin for autophagy–lysosomal degradation through the PI3K/AKT/mTOR pathway inhibition." (PMID 40649987, 2025). "Nevertheless, most importantly, these results suggest a likely relationship between CAVIN1, EMT mechanisms and mTOR regulation in colorectal cancer." (PMID 40269326, 2025). "Inhibiting Carboxypeptidase A6 (CPA6) expression in colorectal cancer can suppress Akt/mTOR signaling activation and inhibit tumor growth." (PMID 41001032, 2025).
colorectal cancer (continued). "In this proof-of-concept study, we investigated the lipidomic and volatilomic profiles of mTOR catalytic inhibitors (mTORci)-resistant and -sensitive colorectal cancer cells." (PMID 40461777, 2025). "This study reveals that phillyrin inhibits CRC cell metastasis and induces apoptosis via the PI3K/AKT/mTOR pathway, highlighting its promise as a potential therapeutic candidate for future colorectal cancer treatment." (PMID 41142018, 2025). "The decrease in the methylarginine level of AKT1 inhibited the AKT/mTOR signaling pathway, consequently decreasing colorectal cancer cell proliferation and resulting in the suppression of colonization." (PMID 40279519, 2025). "According to the study by Thomas, Ras-related protein Rab-1A (RAB1A) overexpression positively correlates with mTOR activation and rapamycin sensitivity in colorectal cancer cell lines." (PMID 41050665, 2025). "Subsequently, it has been reported that FABP4 depletion suppresses the activation of stemness properties in colorectal cancer via modulation of the ERK/mTOR pathway." (PMID 41392988, 2025). "In colorectal cancer, convallatoxin suppresses proliferation and angiogenesis via cooperation between the mTOR/STAT3 and JAK2/STAT3 pathways." (PMID 40321161, 2025). "Consistent with published studies, our study demonstrated that PRMT5 methylates AKT1 at R391 to activate the AKT/mTOR signaling pathway in colorectal cancer cells." (PMID 40279519, 2025). "The expression of mTORC2 components such as Rictor and mTOR is frequently up‐regulated in colorectal cancer patients and knockdown of mTORC2 components results in suppression of cell proliferation and invasion." (PMID 40785580, 2025). "A previous study has shown that at high abundance, naringenin can inhibit colorectal cancer cell growth by repressing the PI3K/AKT/mTOR signaling pathway." (PMID 41226554, 2025). "Preclinical research has shown efficacy of combining mTOR inhibitors with PD‐1/PD‐L1 inhibitors in syngeneic mouse models of renal cell carcinoma oral cavity cancer, and colorectal cancer." (PMID 39258533, 2025). "The mTOR inhibitor dactolisib (BEZ-235), in combination with BMS-1166, promotes apoptosis in colorectal cancer cells by blocking the PI3K/mTOR pathway and disrupting the crosstalk of the MAPK pathway." (PMID 39980564, 2025). "Recent studies have indicated that pharmacological inhibition of the mTOR-PPP axis holds promising potential as a therapeutic strategy against colorectal cancer." (PMID 40303483, 2025). "Despite accumulating evidence of the interplay between ECM remodeling and mTOR signalling across various malignancies, studies specifically linking ECM-related genes to mTOR pathway activation in colorectal cancer remain limited." (PMID 40860666, 2025). "A gene set enrichment analysis (GSEA) of data from patients with colorectal cancer revealed that the activity of the mTOR signaling pathway was negatively correlated with the expression of NEDD4L." (PMID 40279519, 2025). "In vivo experiments have confirmed that the CLDN4 exerts a carcinogenic effect in colorectal cancer through the activation of the PI3K/AKT/mTOR signaling pathway." (PMID 41461671, 2025). "The cytotoxic effects of A. alba Turra extract were tested on colorectal carcinoma cells, and it was associated with apoptosis induction, cell cycle arrest, and the modulation of the PI3K/AKT/mTOR pathway." (PMID 40282790, 2025). "Studies have revealed that circRNA FBXW7 not only inhibits the formation and progression of gliomas, but also inhibits the malignant progression of colorectal cancer and gastric cancer by inhibiting mTOR expression by activating PTEN." (PMID 39727990, 2024). "Research has investigated using both autophagy activators and inhibitors together; for instance, CQ and HCQ have been shown to boost the impact of mTOR inhibitors like temsirolimus or everolimus, in colorectal cancer, melanoma, and neuroendocrine neoplasms." (PMID 39650649, 2024).